MPO (myeloperoxidase)
Diseases named in the same sentence as MPO in open-access papers (continued):
Sharing a sentence is not in itself a finding about the gene and the disease.
systemic vasculitis (continued). "Thus, investigation of respiratory tract involvement according to these surrogate markers will assist the diagnosis of GPA in the cases without histological proof of granuloma/necrotizing vasculitis even in MPO-ANCA positive cases." (PMID 26223225, 2015). "Autoimmune and systemic vasculitis screenings were negative, including anti-nuclear antibody (ANA), anti-neutrophil cytoplasmic antibody (ANCA) [myeloperoxidase (MPO), proteinase 3 (PR3)], complement levels, cryoglobulins, and antiphospholipid antibodies." (PMID 40765604, 2025). "Autoimmune serologies—including anti-MPO, anti-PR3, ANA, and anti-GBM antibodies—were negative, reducing suspicion for systemic vasculitis or lupus nephritis." (PMID 40688963, 2025). "Although myeloperoxidase antineutrophil cytoplasmic antibodies (MPO-ANCA) are often present in patients with MPA, patients with ILD and MPO-ANCA positivity but without other manifestations of systemic vasculitis have also been reported." (PMID 35807120, 2022). "The remaining three MPO-ANCA positive cases were diagnosed as GPA on the basis of the surrogate markers and positivity for ANCA without histological proof of granuloma or necrotizing vasculitis." (PMID 26223225, 2015).
myeloid sarcoma (46 papers, 1959 to 2026). A tumor mass composed of myeloblasts or immature myeloid cells. "King introduced the expression chloroma in 1853 due to the green colouration caused by myeloperoxidase (MPO)." (PMID 39996833, 2025). "Myeloid sarcoma (MS) was first described in 1811 and was called “chloroma” because of the green colour of the lesion, which is caused by the myeloperoxidase content of the cells." (PMID 40291221, 2025). "Due to the green, gross appearance caused by the myeloperoxidase enzyme in immature myeloid cells, it is also known as chloroma." (PMID 36686093, 2022). "MS first described chloroma because of the greenish color, caused by the presence of myeloperoxidase (MPO)." (PMID 36545668, 2022). "Solid extramedullary manifestations of CML historically are termed chloroma because of the greenish color caused by the presence of myeloperoxidase." (PMID 33672937, 2021). "It was first described in 1811 and later named “chloroma” by King in 1853 because of its green colour caused by the presence of myeloperoxidase (MPO)." (PMID 25685570, 2015). "MS, also known as granulocytic/monoblastic sarcoma or extramedullary myeloid tumor, was first known as chloroma, with its macroscopically greenish color caused by production of myeloperoxidase." (PMID 25805673, 2015). "EMS is also known as granulocytic sarcoma or chloroma, since it is diagnosed based on the presence of a green color caused by myeloperoxidase." (PMID 26622785, 2015). "MS was previously referred to as chloroma due to its characteristic greenish color caused by high myeloperoxidase content." (PMID 24744674, 2012). "In our study, the level of MPO mRNA expression in Kikuchi's disease was found to be comparable to that observed in myeloid sarcoma." (PMID 40682358, 2025). "Immunophenotypically, three cases showed a complete lineage switch to myeloid sarcoma, characterized by the complete loss of CD19 and gain of MPO." (PMID 41333696, 2025). "In myeloid sarcoma, MPO is expressed by malignant cells of myeloid lineage, often with neutrophilic differentiation." (PMID 40682358, 2025). "In contrast, one case initially presented with a mixed-phenotype myeloid sarcoma (CD19 retention with partial MPO acquisition) at first relapse, which then evolved into a complete myeloid sarcoma at second relapse." (PMID 41333696, 2025). "Immunophenotyping for monocytic markers, such as CD68, CD163, and MPO, can distinguish CNS chloroma from other neoplastic or inflammatory processes." (PMID 40951121, 2025). "‘Chloroma’ derives from the Greek word ‘chloros’ meaning ‘green’, because of the green colour of the malignancy, due to the oxidation of myeloperoxidase (MPO) within the granules of immature myeloid precursors." (PMID 39458104, 2024). "In AML/myeloid sarcoma, MPO, CD117, CD33, CD34, and TdT are positively expressed but B- and T-lineage markers are negative." (PMID 39559598, 2024). "Myeloid sarcoma is a solid tumor formed by leukemic cells outside the bone marrow and was also called chloroma in the 19th century because the tumors showed a greenish hue from the myeloperoxidase enzyme." (PMID 34929016, 2021). "The term “Chloroma” was devised historically because of its greenish color (Chloros = Green in Greek), which is because of its high MPO content." (PMID 34805008, 2021). "Our case was thought to be in favor of myeloid sarcoma, since MPO-, CD34-, CD117-, HLA-DR-, and LCA-positive immunoreactivity was detected in the tru-cut biopsy specimens performed from lesions showing FDG uptake in bilateral breasts and axillae." (PMID 34325712, 2021). "First described by Burns in 1811, then in 1853, King named GS as “chloroma,” due to its green colored appearance when exposed to air, resulting from the presence of myeloperoxidase in the tumor cells." (PMID 33120806, 2020). "It was first described by Burns in 1811 and termed as chloroma by King in 1853 because a subset of MS contains abundant myeloperoxidase (MPO) and turns green upon exposure to oxygen." (PMID 31699112, 2019).
myeloid sarcoma (continued). "First described by Burns in 1811, the term “Chloroma” was coined by King in 1853 to describe this tumor entity based on its green color which is due to the enzyme myeloperoxidase (MPO) present in the myeloid cells." (PMID 31015077, 2019). "These tumors are also called chloromas due to a greenish color of the tissues imparted by myeloperoxidase present in the cytoplasm of tumor cells." (PMID 28243188, 2017). "Immunohistochemical studies revealed CD34, CD117, and myeloperoxidase (MPO) positive blasts consistent with a diagnosis of myeloid sarcoma." (PMID 25977825, 2015). "Previously referred to as granulocytic sarcoma and also by the name chloroma meaning “green tumor,” MS has a green appearance due to the presence of myeloperoxidase in many of these tumors." (PMID 25478260, 2014). "Histopathological exam of the biopsy taken from the duodenal mass revealed myeloid sarcoma with strongly positive myeloperoxidase." (PMID 25330524, 2014). "Although the first endoscopic exam was negative when the patient was admitted for pancreatic mass, the endoscopic exam was repeated and biopsy of the then-detected mass showed myeloid sarcoma; this was confirmed by myeloperoxidase stain." (PMID 25330524, 2014). "The presence of myeloperoxidase in these myeloid cells gives these masses a greenish coloration and therefore they were historically termed as chloromas." (PMID 21722379, 2011). "Immunohistochemistry can aid in differentiating KFD from lymphomas but should never replace the hematoxylin and eosin evaluation of an adequate sample, as MPO positivity could be misinterpreted as myeloid sarcoma." (PMID 39982355, 2025). "Histopathological examination with immunohistochemistry revealed tumor cells positive for myeloperoxidase and CD34 with a high Ki-67 proliferation index, confirming the diagnosis of multifocal myeloid sarcoma." (PMID 42051833, 2026). "Biopsy of the left inguinal lesion showed MPO positivity, CD34 positivity, partial TdT positivity, and a Ki-67 index of about 80%, supporting myeloid sarcoma." (PMID 42200007, 2026). "The immature nuclear features and expression of the myeloid antigens MPO and CD13 was most consistent with the diagnosis of myeloid sarcoma with monocytic differentiation." (PMID 29463311, 2018). "CT-guided puncture suggested myeloid sarcoma (MS) due to positive immunohistochemistry for MPO, CD45, and Ki-67 and negative CK, CD3, and CD20." (PMID 37480085, 2023). "CD34, MPO, CD117, CD68, and lysozyme positivity also support the diagnosis of myeloid sarcoma." (PMID 33432557, 2021). "MPO, CD117, CD68 positive cells in lymph nodes indicated co-existing myeloid sarcoma." (PMID 33327223, 2020). "MPO and CD117 are the most sensitive markers for myeloid differentiation in myeloid sarcoma." (PMID 25276445, 2014). "MPO and S-100 negativity rule out myeloid sarcoma and metastatic melanoma, respectively." (PMID 23476834, 2013). "A third round of IHC staining was performed, which showed negative expression for myeloperoxidase (MPO) and CD34—ruling out myeloid sarcoma and supporting a diagnosis of lymphoma." (PMID 41158858, 2025). "In this case, CD21 and CD35 were positive and CD45 was weakly positive; T and B cell markers were negative; MPO was positive, but CD117, CD15, and CD68 were negative; therefore, myeloid sarcoma and acute myeloid leukemia were not considered." (PMID 37833728, 2023). "Further immunohistochemical analysis revealed that the tumor was positive for CD43, lysozyme, and myeloperoxidase but negative for CD3, CD20, and CD30, supporting the diagnosis of myeloid sarcoma." (PMID 35036234, 2022). "Flow cytometry showed an immature cell population (CD45 dim) that was negative for CD34, CD56, CD117, and MPO; strongly positive for CD4; and variably positive for CD10, CD33, HLA‐DR, CD68, CD123, and E‐cadherin, consistent with myeloid sarcoma (MS)." (PMID 31788302, 2019).
lung carcinoma (42 papers, 2009 to 2025). "Several epidemiological studies have shown that a polymorphism (-463G → A transition) in the promoter region of the MPO gene decreases the risk of developing lung cancer." (PMID 41254689, 2025). "For example, the Gly463Ala polymorphism located in the promoter region of the myeloperoxidase (MPO) gene has been found to be associated with a lower risk of tobacco-induced lung cancers." (PMID 33113880, 2020). "For instance, the association between MPO-463G > A polymorphism and lung cancer risk has attracted the most attention since the first meta-analysis performed in 2002 and suggested a slight protective effect of the MPO 463 A variant." (PMID 28764808, 2017). "The role of NE and MPO in chronic lung inflammation and association with lung cancer development has been characterized in cell line and animal models." (PMID 23919722, 2013). "The MPO−463G>A polymorphism influences MPO transcription and has been associated with lung cancer susceptibility." (PMID 23840365, 2013). "A polymorphism in the promoter region of MPO (463G>A) has been found to be inversely associated with lung cancer and differences in the association with age and sex have been suggested." (PMID 24212786, 2011). "The inverse association between lung cancer and MPO 463G>A polymorphism was observed equally in males and females in a different study." (PMID 24212786, 2011). "Moreover, patients who express more MPO due to a single-nucleotide polymorphism in the promoter region (-463 G >A, rs#2333227) are the most susceptible to lung cancer, as are those with other chronic inflammatory diseases in which MPO plays a pathogenic role." (PMID 41049128, 2025). "However, studies have associated low MPO expression, due to a polymorphism in the human MPO gene, with a reduced risk of lung cancer." (PMID 37627581, 2023). "Low MPO expression has been linked to a reduced risk of developing lung cancer." (PMID 37627581, 2023). "Interestingly, prior studies have indicated that a single nucleotide polymorphism in the human MPO gene promoter region is associated with reduced MPO levels and lower risk for developing lung cancer." (PMID 24821130, 2014). "Meta-analyses of the MPO −463G>A polymorphism on lung cancer risk." (PMID 23840365, 2013). "Among them, the relationship between lung cancer risk and the MPO−463G>A polymorphism was the most extensively studied, It has been previously suggested that there was an association between the GG+GA genotype of MPO and a decreased risk of lung cancer." (PMID 23840365, 2013). "Therefore, further study of the effects of this MPO polymorphism on lung cancer is warranted, and we included this SNP in our selection." (PMID 19479063, 2009). "Moreover, clinical relevance was supported by findings that PMN-MDSCs from lung cancer patients exhibited increased migration and NETosis in response to C5a, with elevated levels of myeloperoxidase (MPO)-DNA complexes—a hallmark of NETosis—correlating with C5a levels in these patients." (PMID 39555072, 2024). "In addition, we further stratified the digestive system cancer and lung cancer group by ethnicity and found some interesting results that the protect effect of MPO-463G > A polymorphism was only found in Caucasians in lung cancer population and Asians in digestive system cancer population." (PMID 28764808, 2017). "The pro-oncogenic effects of MPO in lung cancer, namely enhanced cellular proliferation and reduced apoptosis, were mediated by the activation of the AKT and ERK signaling pathways via increased phosphorylation." (PMID 41254689, 2025). "In summary, various neutrophil subtypes and their expressed molecules—such as CD74, defensins, PDL1, MPO, NE, and NETs—hold promise as predictive biomarkers for immunotherapy in lung cancer." (PMID 41254689, 2025). "Pharmacological inhibition of MPO with 4-aminobenzoic acid hydrazide was sufficient to reduce the lung cancer burden in mice, as evidenced by a significant decrease in tumor progression." (PMID 41254689, 2025).
lung carcinoma (continued). "Our results highlight the role of MPO as a neutrophil-derived enzyme that can alter the function of lung cancer cells." (PMID 37627581, 2023). "We found that MPO rapidly binds to the surface of lung cancer cells and that the amount of bound enzyme depends on the concentration/availability in the media." (PMID 37627581, 2023). "In this study, we used the human lung cancer cell line (A549 cells) with an epithelial origin to examine the role of MPO in cancer development." (PMID 37627581, 2023). "Blocking MPO from binding to cells or treatment with an MPO inhibitor reduced MPO effects on apoptosis and proliferation of lung cancer cells." (PMID 37627581, 2023). "Our results point to MPO as a neutrophil-derived enzyme that positively impacts the behaviour of lung cancer cells." (PMID 37627581, 2023). "Altogether, we found that enzymatically active MPO plays a role in promoting tumour development of lung cancer cells in vitro and in vivo." (PMID 37627581, 2023). "By inhibiting MPO, groups have observed reduced tumor burden in lung cancer models, as well as a reduction of tumor size in a tumor graft model in MPO‐knockout mice using Lewis lung carcinoma cells." (PMID 38062888, 2023). "We were unable to find studies evaluating serum levels of the monocyte/macrophage activation markers sCD14 or sCD163 or the neutrophil activation marker MPO in relation to survival in lung cancer patients." (PMID 35911763, 2022). "Compared with healthy controls, the level of MPO–DNA complexes in lung cancer patients increased remarkably and was positively correlated with peripheral blood neutrophil counts, smoking status, and poor prognosis." (PMID 35036439, 2022). "Further highlighting the important role of MPO in tumorigenesis, both neutrophils, and specifically MPO have been corelated to tumor size in murine models of lung cancer." (PMID 36293108, 2022). "It is noteworthy that compared with the healthy controls, the levels of MPO–DNA complexes in lung cancer patients increased remarkably." (PMID 35036439, 2022). "This is particularly important in cancers related to cigarette smoke and patients with lung cancer, which have elevated MPO levels in lung tissue and serum." (PMID 36293108, 2022). "It was reported that MPO levels were dramatically enhanced in the bronchoalveolar lavage fluid and positively related to the carcinogenicity of inflammatory in lung cancer formation 43-44." (PMID 31692996, 2019). "Though we still lack direct evidence that supports TAN and TAM interaction through MPO and the MMR, massive MPO-positive neutrophil infiltration has been found in established colorectal cancer and lung cancer." (PMID 26966341, 2016). "That said, our studies suggest that use of MPO inhibitors in early in tumor development is a potential new strategy for lung cancer prevention." (PMID 24821130, 2014). "Serum and BAL fluid levels of both NE and MPO were significantly higher in patients with lung cancer than in patients with COPD or healthy individuals (P < 0.05)." (PMID 23919722, 2013). "We also investigated levels of NE, MPO and ROS production in the patients with different stage of lung cancer (early vs. advanced)." (PMID 23919722, 2013). "During the 5-year period prior to measurement of serum MPO, 149 subjects died and more than half of the deaths were due to lung cancer (38.3%) and cardiovascular disease (24.8%)." (PMID 23637811, 2013). "Our data demonstrated that patients with advanced lung cancer had significantly higher serum NE, MPO levels and more intensive ROS production in peripheral neutrophils than patients with early stage lung cancer." (PMID 23919722, 2013). "In this study, we investigated whether myeloperoxidase can alter the function of A549 human lung cancer cells." (PMID 37627581, 2023). "The effects of MPO in lung cancer development are still unclear." (PMID 37627581, 2023).